SMN1 (survival of motor neuron 1, telomeric)
Diseases named in the same sentence as SMN1 in open-access papers (continued):
Sharing a sentence is not in itself a finding about the gene and the disease.
spinal muscular atrophy (continued). "Spinal muscular atrophy (SMA) is a motor neuron disorder caused by recessive loss-of-function mutations in SMN1." (PMID 39119251, 2024). "Spinal muscular atrophy (SMA) is an autosomal recessive disorder caused by a biallelic mutation in the SMN1 gene, resulting in progressive muscle weakness and atrophy." (PMID 37542300, 2023). "Spinal muscular atrophy (SMA) is a severe motoneuron disease caused by a genetic defect in the SMN1 gene encoding for the survival motoneuron protein SMN1." (PMID 36849544, 2023). "Mutations or deletions in the SMN1 gene result in spinal muscular atrophy (SMA), a neuromuscular disorder with onset mainly during the early childhood." (PMID 36768569, 2023). "Spinal muscular atrophy (SMA) is a congenital neuromuscular disease caused by the mutation or deletion of the survival motor neuron 1 (SMN1) gene." (PMID 36604149, 2023). "The conversion from SMN2 to SMN1 which was found in 6 patients with spinal muscular atrophy (SMA) is causative for disease as a result of a synonymous variant that is introduced in the SMN1 gene." (PMID 37891200, 2023). "Spinal muscular atrophy (SMA) is a progressive neuromuscular disorder caused by a loss of the survival of motor neuron 1 (SMN1) gene, resulting in a loss of spinal motor neurons (MNs), leading to muscle weakness and wasting." (PMID 36930296, 2023). "Nusinersen (Spinraza) is a well-known ASO drug was to treat spinal muscular atrophy associated with a mutation in the SMN1 gene." (PMID 38017459, 2023). "Spinal muscular atrophy (SMA) is a neurodegenerative disorder caused by mutations in the SMN1 gene resulting in reduced levels of the SMN protein." (PMID 37543540, 2023). "A ddPCR-based RMD method has also been employed for NIPD of families at risk of spinal muscular atrophy, involving molecular counting of the copies of the SMN1 gene in cfDNA of mothers who carry only one functional copy." (PMID 39698301, 2023). "Our literature search revealed that the SMN1 gene is the determinant gene for spinal muscular atrophy in humans, a rare hereditary neuromuscular disease caused by deletion and/or mutation of SMN1." (PMID 37893967, 2023). "Spinal muscular atrophy (SMA) is a progressive neuromuscular disease caused by biallelic pathogenic/likely pathogenic variants of the survival motor neuron 1 (SMN1) gene." (PMID 37606479, 2023). "Spinal muscular atrophy (SMA) is an autosomal recessive neuromuscular disorder caused by the deletion or mutation of the survival motor neuron 1 (SMN1) gene." (PMID 37621829, 2023). "Spinal muscular atrophy (SMA) is an autosomal recessive myopathy caused by mutations in the SMN1, resulting in reduced SMN protein levels." (PMID 37892116, 2023). "Spinal muscular atrophy is a disease caused by SMN1 mutations, resulting in decreased levels of SMN protein and subsequent death of spinal motor neurons and denervation of skeletal muscles." (PMID 37146581, 2023). "Spinal muscular atrophy (SMA) is an inherent neuromuscular disease caused by mutation or deletion of the survival motor neuron 1 (SMN1) gene." (PMID 36604149, 2023). "5q-associated spinal muscular atrophy (SMA) is a neurodegenerative autosomal recessive disorder caused by homozygous deletion or mutation in the survival motor neuron 1 gene (SMN1)." (PMID 37280513, 2023). "Spinal muscular atrophy (SMA) is a genetic neuromuscular disease caused by mutations of the SMN1 gene." (PMID 37280513, 2023). "Spinal muscular atrophy (SMA) is a devastating neurodegenerative disease caused by mutations in the SMN1 gene." (PMID 38002071, 2023). "Spinal muscular atrophy (SMA) is a motor neuron disease caused by a decrease in the survival motor neuron (SMN) protein due to SMN1 deficiency." (PMID 35691950, 2023). "Spinal muscular atrophy (SMA) is an autosomal recessive neuromuscular disorder caused by pathogenic variants in the SMN1 gene." (PMID 37799281, 2023).
spinal muscular atrophy (continued). "Deletions or, less frequently, mutations of the telomeric SMN1 gene, represent the diagnostic parameter of spinal muscular atrophy (SMA), one of the most common pediatric genetic diseases." (PMID 36769246, 2023). "Loss of survival of motor neuron 1 (SMN1) gene was found in 1995 as responsible for the monogenic pathology spinal muscular atrophy (SMA)." (PMID 36882285, 2023). "Spinal muscular atrophy (SMA) is a lower motor neuron disease due to biallelic mutations in the SMN1 gene on chromosome 5." (PMID 38020652, 2023). "Spinal muscular atrophy (SMA) is a rare genetic disorder caused by mutations in the SMN1 gene, leading to the progressive degeneration of motor neurons and ultimately to muscle weakness and atrophy." (PMID 37895887, 2023). "5q-associated spinal muscular atrophy (SMA) is a rare genetic disease caused by mutations in the SMN1 gene, resulting in a loss of functional SMN protein and consecutive degeneration of motor neurons in the ventral horn." (PMID 37289324, 2023). "5q-associated spinal muscular atrophy (SMA) is a rare genetic disease caused by homozygous deletions or compound heterogeneous mutations in the SMN1 gene, resulting in a loss of functional survival motor neuron (SMN) protein." (PMID 37289324, 2023). "The vast majority of severe (Type 0) spinal muscular atrophy (SMA) cases are caused by homozygous deletions of survival motor neuron 1 (SMN1)." (PMID 37841286, 2023). "Beyond motor neuron degeneration, homozygous mutations in the survival motor neuron 1 (SMN1) gene cause multiorgan and metabolic defects in patients with spinal muscular atrophy (SMA)." (PMID 37957344, 2023). "Splicing rescue of exon 7 in SMN2 makes up for the loss-of-function of the paralogous gene, SMN1, which is mutated in spinal muscular atrophy (SMA) patients." (PMID 37301863, 2023). "Spinal muscular atrophy (SMA) is a genetically inherited recessive neuromuscular disease caused by mutations in the survival motor neuron 1 (SMN1) gene located in the 5q13 region on chromosome 5." (PMID 35606491, 2023). "Spinal muscular atrophy (SMA) is an autosomal recessive disease characterized by deletion or mutation in the survival motor neuron 1 gene (SMN1)." (PMID 37598295, 2023). "Although the loss of the survival motor neuron 1 gene (SMN1) was identified in 1995 to be responsible for spinal muscular atrophy (SMA), SMA still remains the leading genetic cause of infant mortality." (PMID 36375840, 2023). "Spinal muscular atrophy usually associated with a defect of the survival motor neuron 1 (SMN-1) gene." (PMID 35033190, 2022). "Classical Spinal Muscular Atrophy (SMA) due to the homozygous loss of exon 7 (± exon 8) of SMN1 results in a critical loss of protein production and progressive degeneration of the lower motor neurons of the spinal cord." (PMID 35331287, 2022). "Spinal muscular atrophy (SMA) is a severe neuromuscular disorder caused by biallelic loss or pathogenic variants in the SMN1 gene." (PMID 35955418, 2022). "Low levels of SMN due to deletion or mutation of SMN1 gene causes spinal muscular atrophy (SMA), one of the leading genetic diseases associated with infant mortality." (PMID 35847983, 2022). "Spinal muscular atrophy (SMA) is an autosomal recessive motor neuron disease that is caused by deletions or mutations in the Survival Motor Neuron 1 (SMN1) gene but retention of its nearly perfect orthologue SMN2." (PMID 35741345, 2022). "Spinal muscular atrophy (SMA) is an autosomal recessive neuromuscular disease caused by loss of survival motor neuron 1 (SMN1) gene function and is a primary genetic cause of infant death." (PMID 36140824, 2022). "SMN1 is required for the survival of motor neurons, and mutations in this gene are responsible for spinal muscular atrophy." (PMID 34859816, 2022). "Mutations or deletions of SMN1 cause spinal muscular atrophy (SMA), a leading genetic cause of infant mortality." (PMID 35885927, 2022).
spinal muscular atrophy (continued). "Spinal muscular atrophy (SMA) is a devastating autosomal recessive motor neuron disease associated with mutations in the survival motor neuron 1 (SMN1) gene, the leading genetic cause of infant mortality." (PMID 35887289, 2022). "Spinal muscular atrophy (SMA) is a devastating neuromuscular disorder caused by recessive mutations in the SMN1 gene, globally affecting ~8–14 newborns per 100,000." (PMID 36142791, 2022). "Spinal muscular atrophy associated with mutations in the SMN1 gene (SMA5q) is a genetic neurodegenerative disease, inherited as an autosomal recessive trait." (PMID 36504644, 2022). "Loss-of-function mutations in the SMN1 gene cause the disease spinal muscular atrophy (SMA), which is characterised by the selective loss of alpha motor neurons of the spinal cord, muscle wasting and, in most severe cases, premature death in infancy." (PMID 35877682, 2022). "Deletions or mutations of SMN1 lead to spinal muscular atrophy (SMA), a devastating neurodegenerative disease linked to a high rate of infant mortality." (PMID 35885927, 2022). "Spinal muscular atrophy (SMA) is a childhood motor neuron disease caused by anomalies in the SMN1 gene." (PMID 35551393, 2022). "Spinal muscular atrophy (SMA) is an autosomal-recessive neurodegenerative disease caused by mutations in the survival of motor neuron 1 (SMN1) gene." (PMID 35603786, 2022). "Spinal muscular atrophy (SMA) is caused by deletions or mutations of the survival motor neuron 1 (SMN1) gene." (PMID 35163320, 2022). "Spinal Muscular Atrophy (SMA) is a neuromuscular condition characterised by biallelic mutations of the Survival Motor Neuron 1 (SMN1) gene." (PMID 36542615, 2022). "Spinal muscular atrophy (SMA) is an autosomal recessive neuromuscular disease caused by deletion or mutation of the SMN1 gene." (PMID 34721262, 2021). "Spinal muscular atrophy is a motor neuron disease that is caused by mutations in the survival of motor neuron 1 gene (SMN1), resulting in reduced levels of SMN protein." (PMID 34434089, 2021). "SMN1 mutations cause spinal muscular atrophy, a severe disease associated with a progressive loss of motoneurons." (PMID 34882671, 2021). "SMN1 gene mutations or deletions result in spinal muscular atrophy (SMA), a devastating neurodegenerative disorder characterized by the progressive loss of motor neurons and skeletal muscle atrophy." (PMID 34413305, 2021). "Spinal muscular atrophy (SMA) is an autosomal recessive neuromuscular disorder caused by loss-of-function mutations in the survival motor neuron 1 (SMN1) gene." (PMID 33575118, 2021). "Deficiency of SMN1/2 is usually associated with spinal muscular atrophy; however, it was shown that low levels influence muscle differentiation and maturation through the AKT signalling pathway." (PMID 34445314, 2021). "5q‐associated spinal muscular atrophy (SMA) is a rare monogenic lower motor neuron disease caused by mutations in the telomeric survival of motor neuron 1 (SMN1) gene leading to insufficient SMN protein levels." (PMID 33792208, 2021). "Mutation or deletion of the SMN1 gene is a major cause of spinal muscular atrophy, through deficiency of SMN." (PMID 34573328, 2021). "SMN proteins are correlated with neurodegenerative disorders, such as mutations in the human SMN1 gene, which are linked to spinal muscular atrophy (SMA)." (PMID 34638646, 2021). "Spinal muscular atrophy (SMA) is a neuromuscular disorder caused by mutations in the survival motor neuron 1 (SMN1) gene." (PMID 33575118, 2021). "Homozygous mutation or deletion of the human SMN1 gene causes a devastating neuromuscular disease called Spinal Muscular Atrophy (SMA)." (PMID 34181727, 2021). "Spinal muscular atrophy (SMA) is an autosomal recessive motor neuron disease of variable clinical severity that is caused by mutations in the survival motor neuron 1 (SMN1) gene." (PMID 33821292, 2021).
spinal muscular atrophy (continued). "Spinal Muscular Atrophy is an autosomal recessive disorder that is caused by either homozygous deletions or loss of function mutations in the survival motor neuron 1 (SMN1) gene resulting in a deficiency of survival motor neuron (SMN) protein." (PMID 34484106, 2021). "Spinal muscular atrophy (SMA) type 1 is a severe infantile autosomal-recessive neuromuscular disorder caused by a survival motor neuron 1 gene (SMN1) mutation and characterized by progressive muscle weakness." (PMID 33919289, 2021). "Spinal muscular atrophy (SMA) is caused by homozygous mutations leading to reduced amounts of SMN1 protein." (PMID 33996898, 2021). "Spinal muscular atrophy (SMA) is caused by homozygous survival of motor neurons 1 (SMN1) gene deletion, leaving a duplicate gene, SMN2, as the sole source of SMN protein." (PMID 34638572, 2021). "Spinal muscular atrophy (SMA) is an autosomal recessive motor neuron disorder caused by homozygous loss of function of the SMN1 gene." (PMID 34093395, 2021). "Recent developments have also included the detection of exon 7 of SMN1 in a single reaction for the diagnostic testing of Spinal Muscular Atrophy." (PMID 32765500, 2020). "Spinal muscular atrophy (SMA) is a neurogenetic disorder caused by loss of or pathogenic variants in the survival motor neuron 1 gene (SMN1) on chromosome 5q13, which leads to reduced SMN protein levels and a selective dysfunction of motor neurons." (PMID 32039859, 2020). "Spinal muscular atrophy (SMA) is caused by genetic defects in the survival motor neuron 1 (SMN1) gene that lead to SMN deficiency." (PMID 32031328, 2020). "Spinal muscular atrophy (SMA) is a severe neuromuscular disorder caused by loss of the survival motor neuron 1 (SMN1) gene." (PMID 32587237, 2020). "Spinal muscular atrophy (SMA) is caused by homozygous LoF mutations in the SMN1 gene that is ubiquitously expressed in the body." (PMID 33324928, 2020). "Spinal muscular atrophy (SMA) is largely linked to deletion or mutation of the Survival motor neuron 1 (SMN1) gene located on chromosome 5q13." (PMID 33168084, 2020). "It is thought that this gene, modifier of spinal muscular atrophy, is a mutation in a neighboring gene SMN1." (PMID 32555294, 2020). "Deletions encompassing exon 7 in SMN1 are the most frequent molecular cause of spinal muscular atrophy (SMA), while the number of SMN2 copies has been associated with severity and onset time of SMA24–26." (PMID 32944285, 2020). "In spinal muscular atrophy (SMA) mutations in the SMN1 gene, encoding for the survival motor neuron protein (SMN), is the cause of the disease." (PMID 32435641, 2020). "The defective human survival motor neuron 1 (SMN1) gene leads to spinal muscular atrophy (SMA), the most common genetic cause of infant mortality." (PMID 31991812, 2020). "The motor neurodegenerative disease spinal muscular atrophy (SMA) is caused by alterations of the survival motor neuron 1 (SMN1) gene involved in RNA metabolism." (PMID 32363199, 2020). "Spinal muscular atrophy (SMA) is a neuromuscular disease caused by mutations in survival motor neuron 1 (SMN1)." (PMID 32644120, 2020). "Spinal muscular atrophy is devastating inherited neuromuscular disease resulting from variants of SMN1 and deficiency of the survival motor neuron protein (SMN)." (PMID 32337852, 2020). "Spinal Muscular Atrophy (SMA) is a monogenic neuromuscular syndrome triggered due to mutations in Survival of motor neurone 1 (SMN1) gene." (PMID 32390854, 2020). "If mitochondria are unable to counterbalance cell dysfunction, a secondary mitochondrial disease will appear, like spinal muscular atrophy (SMA) (usually caused by a mutation in SMN1) or Duchenne muscular dystrophy (DMD) due to mutation in DMD)." (PMID 33050147, 2020). "Spinal muscular atrophy (SMA) is a typical example of CB-related disease that is mainly caused by the mutations in the SMN1 gene." (PMID 32764415, 2020).
spinal muscular atrophy (continued). "Spinal Muscular Atrophy (SMA) is caused by homozygous mutations in the human survival motor neuron 1 (SMN1) gene." (PMID 30563832, 2019). "Spinal Muscular Atrophy (SMA) is a childhood form of motor neuron disease that is caused by homozygous loss of the SMN1 gene." (PMID 31273192, 2019). "The molecular genetics underlying spinal muscular atrophy (SMA) have been well established since 1995 with the discovery that it results from deletion or mutation of the survival motor neuron 1 (SMN1) gene encoding the survival motor neuron (SMN) protein." (PMID 30792629, 2019). "Spinal muscular atrophy (SMA) is a pediatric neuromuscular disorder caused by mutation or loss of the human survival motor neuron 1 (SMN1) gene." (PMID 30563832, 2019). "Spinal muscular atrophy (SMA) is caused by mutations/deletions in the survival motor neuron 1 (SMN1) gene, resulting in decreased SMN protein expression and degeneration of spinal cord and brainstem alpha motor neurons." (PMID 31127730, 2019). "Spinal muscular atrophy (SMA) is a severe congenital motor neuron degenerative disease caused by loss-of-function mutations in the survival motor neuron gene 1 (SMN1)." (PMID 31130987, 2019). "Background: 5q spinal muscular atrophy (SMA) is an autosomal recessive lower motoneuron disease caused by deletion or mutations in the survival motor neuron 1 gene (SMN1) which results in reduced expression of full-length SMN protein." (PMID 31736847, 2019). "Spinal muscular atrophy (SMA) is caused by loss-of-function mutations in the survival of motoneuron gene 1 (SMN1)." (PMID 31127156, 2019). "Spinal Muscular Atrophy (SMA) is a childhood motor neuron disease caused by mutations or deletions within the SMN1 gene." (PMID 31273192, 2019). "Spinal Muscular Atrophy results from loss-of-function mutations in SMN1 but correcting aberrant splicing of SMN2 offers hope of a cure." (PMID 31127278, 2019). "Non‐SMN1‐related spinal muscular atrophies are caused by variants in a number of genes, including VRK1, encoding the vaccinia‐related kinase 1 (VRK1)." (PMID 31560180, 2019). "Spinal Muscular Atrophy (SMA) is a rare autosomal recessive disorder caused by a pair of missing or defective Survival of Motor Neuron 1 (SMN1) genes." (PMID 30870495, 2019). "Spinal Muscular Atrophy (SMA) is a rare genetic disease related to the mutations of SMN1 gene which manifests itself with a progressive impairment and atrophy of muscles resulting from the loss of motor cells of the spinal cord." (PMID 30732590, 2019). "Spinal muscular atrophy (SMA) is a progressive motor neuron disease caused by deleterious variants in SMN1 that lead to a marked decrease in survival motor neuron (SMN) protein expression." (PMID 29790918, 2018). "More recently, CPP-PMOs have been explored in preclinical models of spinal muscular atrophy (SMA) whereby mutations in the SMN1 gene results in the loss of survival motor neuron (SMN) protein and subsequent severe motor developmental delay and premature death." (PMID 29734750, 2018). "Nonsense mutations in the SMN1 gene lead to a juvenile form of motor neuron disease called spinal muscular atrophy (SMA)." (PMID 29584802, 2018). "Spinal muscular atrophy (SMA) is a devastating motor neuron disorder caused by homozygous loss of the survival motor neuron 1 (SMN1) gene and insufficient functional SMN protein produced by the SMN2 copy gene." (PMID 30188931, 2018). "Spinal muscular atrophy (SMA) is a motor neuron disease caused by homozygous mutations in the survival motor neuron 1 (SMN1) gene that are partially compensated by the paralogous SMN2 gene." (PMID 29895323, 2018). "Spinal muscular atrophy (SMA) is a severe motor neuron (MN) disease caused by the deletion or mutation of the survival motor neuron 1 (SMN1) gene, which results in reduced levels of the SMN protein and the selective degeneration of lower MNs." (PMID 29941967, 2018).